TLR4 (toll like receptor 4)
Diseases named in the same sentence as TLR4 in open-access papers (continued):
Sharing a sentence is not in itself a finding about the gene and the disease.
COVID-19 (continued). "To determine whether TLR4-mediated ACE2 surface translocation in myeloid populations is also associated with COVID-19 severity, we treated peripheral blood cells from the same patient cohorts ex vivo with LPS for 4 h." (PMID 36085197, 2022). "It has been strongly suggested that TLR-4 can also be associated to severe COVID-19." (PMID 35062298, 2022). "Several TLRs may be implicated in COVID-19 and in the effects of COVID-19 vaccines; however, the strongest evidence provisionally points to TLR4 and TLR2." (PMID 36142792, 2022). "From the currently available data, it is assumed that TLRs, mainly TLR2 and TLR4, may play a pathogenic role by inducing hyperinflammation, and thus, may lead to severe COVID-19." (PMID 34835108, 2021). "Recent studies have found that the production of IL-1β, IL-18, TNF-α, and IL-6 was high in severe COVID-19 patients especially those with severe respiratory failure and are linked to the cytokine storm; these cytokines are downstream of the TLR4 canonical MyD88-dependent pathway." (PMID 33505220, 2021). "The TLR4 signaling response in COVID-19 may cause influenza to induce acute lung injury/acute respiratory distress syndrome or a TLR4-dependent “cytokine storm” similar to septic shock." (PMID 33352889, 2020). "ROC curve showed also that the elevation of serum TLR-4 could be a potential diagnostic marker of high CSS among COVID-19 patients with (AUC = 0.78 ± 0.06; P value = 0.0001*), but the association with hypoxia was non-significant with (AUC = 0.63 ± 0.08 p = 0.1)." (PMID 36864077, 2023). "Our data support the notion that the host’s genetic background can significantly affect COVID-19 clinical phenotype, also suggesting that the IL18-rs1834481, TLR2-rs5743708, and TLR4-rs4986791 polymorphisms may be used as molecular predictors of COVID-19 clinical phenotype." (PMID 37766191, 2023). "Future studies on COVID-19 mortality risk should address pregnancy and high-risk pregnancy, particularly for women with genotypic variations associated with early onset preeclampsia, such as variant TLR-4 alleles, and mutant angiotensin type I and type II receptor combination genotypes." (PMID 35330352, 2022). "Hence, TLR-4 could be used as a targeting protein for neurological complications associated with COVID-19." (PMID 35885104, 2022). "Additionally, TLR4 polymorphisms are associated with COVID-19 severity; the TLR4 minor alleles 299Gly (G) and 399Ile (T) are associated with increased likelihood of severe COVID-19 and the risk of developing cytokine storm." (PMID 36419185, 2022). "Thus, we suggest that activation of the TLR4 pathway in patients with COVID-19 may be linked to poor patient outcomes." (PMID 35784579, 2022). "In addition, SARS-CoV-2’s ability to activate TLR-4 could predispose COVID-19-infected patients to neuro-inflammation, neurodegeneration and alpha-synuclein aggregation." (PMID 35888166, 2022). "In COVID-19, TLR4 upregulation correlates with systemic cytokine storm and lung–brain axis inflammation, positioning it as a shared upstream driver of immune amplification." (PMID 41007696, 2025). "TLR4 and its downstream signaling molecules, including CD14, MyD88, and TRAF6, are up-regulated in renal tubular and renal endothelial cells in COVID-19 patients, and are closely associated with acute tubular necrosis and increased kidney injury." (PMID 40584714, 2025). "Elevated levels of TLRs such as TLR2 and Toll-Like Receptor 4 (TLR4), alongside increased expression of the Nuclear Factor Kappa B (NF-κB) transcription factor, were observed more so in severe compared to moderate COVID-19 patients." (PMID 39928675, 2025). "COVID-19-induced brain dysfunction correlates with TLR4 signaling in microglia driven by spike proteins." (PMID 40491910, 2025). "Recently, several derivatives of KRN7000 have been developed for use as adjuvants in COVID-19 subunit vaccines, immunostimulating agents, and Toll-like receptor 4 (TLR4) agonists." (PMID 40943381, 2025).
COVID-19 (continued). "In this context, the following TLRs have been associated with the severity of COVID-19: TLR2, TLR3, TLR4, TLR7, TLR8 and TLR9." (PMID 41011507, 2025). "Different major dysregulated biosignatures including but not limited to Interferon Alpha 1 (IFNA1), Interferon Alpha Inducible Protein 6 (IFI6), Toll-Like Receptor 4 (TLR4) and interleukin-6 (IL6) are linked to host responses to COVID-19." (PMID 39040605, 2024). "A second study investigated the possible contribution of SNPs in TLR2 and TLR4 genes to COVID-19 disease severity and prognosis in an European population (N = 249) consisting mainly of Greek patients with SARS-CoV-2 infection." (PMID 38433829, 2024). "Neutrophil extracellular traps (NETs), which are actively formed in severe COVID-19 patients, can also activate various pattern recognition receptors, including TLR4 and TLR7, thereby facilitating the release of inflammatory mediators." (PMID 39457048, 2024). "We analyzed the influence of demographics, pre-existing conditions, inflammatory parameters at the time of hospitalization, and TLR4 rs4986790 genotype on the outcome of COVID-19 in a comprehensive cohort (N = 1570)." (PMID 38433829, 2024). "Another clinical study observed that S100A9, an endogenous ligand of TLR4, was highly upregulated in COVID-19 severe patients compared to healthy controls, and this increase was conversely correlated with plasma album in levels." (PMID 38287815, 2024). "The persistently high interleukin-6 (IL-6) and tumor necrosis factor-α (TNF-α) levels in severe COVID-19 patients are important products of toll-like receptor 4 (TLR4) signaling." (PMID 38165854, 2024). "The remaining IL6R, IFNG, TLR4, and TLR2 genes (feature gene) were the most likely COVID-19 pathogenic genes that progressed into CRS." (PMID 38165854, 2024). "They showed a significantly increased risk of severe COVID-19 in carriers of TLR2 rs57443708 and/or TLR4 rs4986791 variants." (PMID 38433829, 2024). "TLR4 rs4986790 (c.896A>G) genotype distribution among all patients with SARS-CoV-2 infection according to the severity of COVID-19." (PMID 38433829, 2024). "Previous studies have underscored the up-regulation of TLR4 in severe COVID-19 patients, implicating it in augmented ACE2 expression and ensuing hyperinflammation." (PMID 38414855, 2024). "Increased levels of proinflammatory cytokines, the expression of which is activated by TLR4 signaling pathways, are observed in COVID-19 patients." (PMID 39457048, 2024). "Meanwhile, the correlation analysis of ICD-related DEGs and immune cell infiltration in severe COVID-19 showed that TLR4, PIK3CA, FOXP3, ENTPD1, CD4, CASP1 and BAX were significantly correlated with a variety of immune cell infiltration." (PMID 38600309, 2024). "However, the role of TLR4 in the CRS associated with COVID-19 remains unclear." (PMID 38165854, 2024). "Patients with severe COVID-19 exhibit less pronounced increases in TLR4 expression on CD14 monocytes than those with mild COVID-19, which is related to activation of TLR4/NF-κB axis after lipopolysaccharide stimulation." (PMID 38455049, 2024). "The literature suggests that the pathophysiology of COVID-19 involving the pericardium lies within its ability to stimulate innate immune system pathways, such as complement, TLR4, and inflammasome pathways." (PMID 39003456, 2024). "In such a context, blocking TLR4 signalling, which has been proposed as a possible therapeutic approach in COVID-19 patients, arises as a relevant option to attenuate the direct actions of the S protein as an isolated viral element." (PMID 38225643, 2024). "TLR4 and some of its mediated inflammatory signalling molecules are reported to be upregulated in severe COVID-19 patients." (PMID 37777557, 2023). "(2021) suggest TLR4's role in severe COVID-19 is due to synergistic immune activation induced by SARS-CoV-2-bacterium/fungus coinfection." (PMID 37777557, 2023).
COVID-19 (continued). "Only one, very limited, study of AM in severe COVID-19 appears to have been carried out so far, which found activation of TLR4 and TLR9, suggesting both bacterial and viral triggers." (PMID 36769320, 2023). "The manipulation of the TLR4 signaling pathway has emerged as a potential therapeutic avenue for mitigating COVID-19 complications." (PMID 38022594, 2023). "Their phenotype, activation status, TLR4, and chemokine receptors were analyzed by flow cytometry and confirmed that severe COVID-19 patients have increased LPS levels and systemic inflammation that result in monocyte activation." (PMID 37894850, 2023). "Our present work shows the efficiency of NIR light exposure in downregulating the TLR4/NF-κB inflammatory pathway, which is shared by other viral pathologies in addition to COVID-19." (PMID 37891903, 2023). "In the current study have been studied the relation between the levels of serum IL-10, TNF-α, INF-γ and TLR-4 and the presence of lymphopenia in COVID-19 patients group." (PMID 36864077, 2023). "We found that TLR4 and ABCA1 were associated with the infiltration of various immune cells and were highly expressed in CD16 monocytes in severe COVID-19 patients." (PMID 38022594, 2023). "Taken together, these findings suggest pleiotropic effects of TLR4 inhibition in human MΦ, indicating novel potential therapeutic options for the treatment of patients affected by severe COVID-19." (PMID 38034686, 2023). "The study revealed a pattern of decreased expression of DNMT genes (DNMT3A and DNMT3B) and an increase in the methylation of the TNF-α and TLR4 promoters in COVID-19 patients, as well as a correlation between global methylation and disease severity." (PMID 36840831, 2023). "Our investigation likewise revealed an elevation in TLR4 levels in the blood samples of COVID-19 patients with AMI." (PMID 38022594, 2023). "A highly significant increase in the level of serum TLR-4 in COVID-19 patients with CSS > 19 compared to patients with CSS < 19 and also in patients with hypoxia was observed in the current study." (PMID 36864077, 2023). "To investigate the expression patterns of ABCA1 and TLR4 in immune cells, we analyzed scRNA-seq data from PBMCs of COVID-19 patients and healthy controls." (PMID 38022594, 2023). "According to some reported studies, upregulation of TLR4 and the subsequent inflammatory signaling detected in COVID-19 patients “mimics bacterial sepsis”." (PMID 37894850, 2023). "Distinctive features of severe COVID-19 cases in comparison to healthy controls and mild COVID-19 patients encompass heightened TLR4 activity." (PMID 38022594, 2023). "The heat map of gene-immune cell relationship revealed a positive link between ABCA1 and TLR4 in COVID-19 and AMI, particularly TLR4 with a range of immune cells including NK cells, neutrophils, eosinophils, dendritic cells, and macrophages." (PMID 38022594, 2023). "Clinical studies have already shown that antagonizing TLR4 signaling dampens the pathological cytokine storm observed in patients with severe acute COVID-19 and reduces mortality rates in hospitalized COVID-19 patients." (PMID 37915075, 2023). "We investigated the engagement of SARS-CoV-2 with TLR4 in order to better understand how to tackle hyperinflammation in COVID-19." (PMID 38034686, 2023). "Measurement of serum levels of IL-10, TNF-α, INF-γ and TLR-4 showed a highly significant increase in their levels in the COVID-19 patients compared to controls (P value = 0.0001*)." (PMID 36864077, 2023). "The results showed that TLR4 and ABCA1 had moderate to good diagnostic values in COVID-19 and AMI, with TLR4 performing better than ABCA1 (AUC in COVID-19: TLR4, 0.836; ABCA1, 0.775." (PMID 38022594, 2023). "Our study combining human lung transcriptomics with functional studies in human macrophages clearly supports the design and development of TLR4 - directed therapeutics to mitigate hyperinflammation in severe COVID-19." (PMID 38034686, 2023).
COVID-19 (continued). "The current study found that, serum level of TLR4 was higher in COVID-19 group compared to control group (P value = 0.0001)." (PMID 36864077, 2023). "A case–control study included 25 COVID-19 and 10 healthy controls illustrated that TLR4-dependent platelet activation contribute in the development of thrombosis and coagulopathy in severely affected COVID-19 patients compared to controls." (PMID 37383608, 2023). "Oleuropein was investigated against the SARS-CoV-2 target (main protease 3CLpro), TLR-4, and Prolyl Oligopeptidases (POP), to explore oleuropein potency against the neurological complications associated with COVID-19." (PMID 36985442, 2023). "In detail, our digital pathology based immunohistochemistry showed a mean count of TLR-4 positive macrophages of 183.04 ± SEM 54.9 in COVID-19 patients, versus mean count of 42.67 ± SEM 10.2 in control cases." (PMID 37686069, 2023). "LPS-induced CD45 expression was lower in COVID-19 patients than in healthy volunteers in all three investigated cell types, suggesting a downregulation of the Toll-like receptor-4-mediated signal transduction pathway in COVID-19, at least in respect to CD45." (PMID 35887979, 2022). "NRP-1 mRNA expression level had a significant positive (p = 0.000) correlation with both TLR2 and TLR4 mRNA expressions in moderate COVID-19 patients." (PMID 35891270, 2022). "Meanwhile, it has been covered that TLR4 as well its downstream signaling mediators are notably upregulated in peripheral blood monocytes in COVID-19 patients compared to control individuals." (PMID 36188605, 2022). "Statins have potential effects to reduce the cytokine release syndrome in COVID-19 by inhibiting Toll-like receptor 4 (TLR4) and down-modulating macrophage activity." (PMID 35835835, 2022). "In this way, a promising line of research is the evaluation of the role of TLR4 antagonists in myocarditis related to COVID-19." (PMID 36498573, 2022). "Taken together, these experiments demonstrate that the ability of monocytes to mount an appropriate proinflammatory response is impaired in patients with severe COVID-19 upon stimulation through TLR4 or TLR7/8." (PMID 35380990, 2022). "A study reported increased TLR4 expression in myocardium of COVID-19 patients resembles the significant increase of TLR4 expression in bacterial sepsis myocardium." (PMID 36188605, 2022). "Together, these data suggest an association of MyD88 and a panel of TLRs (i.e., TLR1, TLR2, TLR4, TLR5, TLR8, and TLR9) with disease progression in patients with COVID-19." (PMID 35682644, 2022). "In the current study, oleuropein was investigated against SARS-CoV-2 target (main protease 3CLpro), TLR-4 and Prolyl Oligopeptidases (POP), to explore oleuropein potency against the neurological complications associated with COVID-19." (PMID 35885104, 2022). "In WT cells, S100a8 production is generally suppressed upon TLR4 activation, analogous to clinical studies which show that circulating calprotectin levels remain low in majority of the COVID-19 patients who are asymptomatic or have mild symptoms." (PMID 36172386, 2022). "The inhibition of TLR4 or IL-1β has therefore been proposed as a mechanism to alleviate COVID-19 symptoms." (PMID 35631059, 2022). "ACE2 mRNA expression level exhibited a significant positive (p = 0.000) correlation with both TLR2 and TLR4 mRNA expressions in the severe COVID-19 group." (PMID 35891270, 2022). "In the current study, TLR2 and TLR4 showed significantly higher expression in the blood of moderate and severe COVID-19 patients than in healthy individuals." (PMID 35891270, 2022). "In an attempt to identify the factors responsible for the cytokine storm seen in severe cases of COVID-19, genes involved in the TLR4 pathway were found to be highly upregulated." (PMID 35631059, 2022). "Glycyrrhizin is an active ingredient and has potential effect to be used to control COVID-19 because of its dual antiviral action and TLR4 antagonism." (PMID 36188605, 2022).
COVID-19 (continued). "HMOS hold great promise for the prevention and treatment of COVID-19 by four modes of action, including competitive inhibition (receptor decoy), anti-inflammatory and other immunomodulation, mucosal signaling with TLR4 inhibition, and prebiotic action." (PMID 35203555, 2022). "The TLR2 and TLR4 mRNA expression levels were significantly higher (p < 0.01) in moderate and severe COVID-19 groups than in the healthy control group." (PMID 35891270, 2022). "TLR4-mediated production of IL-6 and TNF-α is associated with the severity of COVID-19 in patients with cardiometabolic comorbidities." (PMID 35356515, 2022). "Mitogen-activated protein kinase 14 (MAPK14), angiotensin-converting enzyme (ACE), toll-like receptor (TLR4), and MAPK8 are the main players that are directly linked to the majority of the phytocompounds and played a major role in COVID-19-associated pathways." (PMID 36144690, 2022). "Researchers want to trace the connecting link between neurological complications and COVID-19, and Toll-like receptor 4 (TLR4) gives off an impression of being one such link." (PMID 35885104, 2022). "MAPK14, ACE, TLR4, and MAPK8 genes are present in all the compounds, and these genes are associated with COVID-19 pathways." (PMID 36144690, 2022). "Toll-like receptor 4, an innate immune sensor, is one of the key 'fate-deciding' regulators of immunity as well as COVID-19 immunopathogenesis." (PMID 35462619, 2022). "As S protein from SARS-CoV-2 Delta and Omicron variants can activate TLR4-driven calprotectin production in Dok3-/- neutrophils, our study suggests that targeting calprotectin production may be an effective strategy to combat severe COVID-19 manifestations associated with these emerging variants." (PMID 36172386, 2022). "By taking the intersection of COVID-19/HCC genes and vitamin D-associated targets, we obtained seven overlapping genes (HMOX1, MB, TLR4, ALB, TTR, ACTA1 and RBP4) of vitamin D against COVID-19/HCC." (PMID 36275701, 2022). "In fact, the cytokine storm generated after TLR-4 activation/binding with the spike protein of SARS-CoV-2 causes neuro-inflammation and neuro-degeneration in COVID-19 patients." (PMID 35888166, 2022). "Recently, there have been several studies pointing to the role of TLR4 in the pathogenesis of COVID-19." (PMID 35682644, 2022). "TLR4 antagonists have previously been shown to be promising drugs preventing the development of cytokine storm in patients with COVID-19." (PMID 36290634, 2022). "To date, several phase I/II clinical trials have been conducted to evaluate the efficacy of TLR4 modulators in COVID-19 (Clinicaltrials.gov NCT02735707, NCT04401475, NCT04479202)." (PMID 35203555, 2022). "Studies have shown that treatment with appropriate TLR4 antagonists late in the development of COVID-19 patients can inhibit excessive TLR4 expression and thus inhibit inflammatory cytokine storms." (PMID 36188605, 2022). "Perhaps the best evidence that TLR4 has a role in SARS-CoV-2 infection is the observation that TLR4 mediated inflammatory signaling molecules are upregulated in peripheral blood mononuclear cells from COVID-19 patients, compared with healthy controls." (PMID 34030677, 2021). "Supporting evidence has shown that elevated levels of TLR4 downstream signaling molecules have been observed in patients with COVID-19." (PMID 33498183, 2021). "Here, we review and connect evidence for SARS-CoV-1 and SARS-CoV-2 having direct and indirect binding to TLR4, together with other viral precedents, which when combined shed light on the COVID-19 pathophysiological puzzle." (PMID 33505220, 2021). "Uncontrolled TLR4-mediated inflammation has been suggested to contribute to immunopathological consequences in COVID-19 patients." (PMID 33498183, 2021). "Some other studies have revealed the pathologic role of TLR-4 in hyperinflammation occurring in COVID-19 patients." (PMID 34659656, 2021).